ERBB2 (erb-b2 receptor tyrosine kinase 2)
Diseases named in the same sentence as ERBB2 in open-access papers (continued):
Sharing a sentence is not in itself a finding about the gene and the disease.
rectal cancer (46 papers, 2009 to 2025). A primary or metastatic malignant neoplasm that affects the rectum. "Frequencies of tumor KRAS, BRAF, and PIK3CA point mutations and ERBB2 amplification in 63 patients with locally advanced rectal cancer." (PMID 23226389, 2012). "Point mutations in KRAS, BRAF, and PIK3CA and ERBB2 amplification were determined in primary tumors from 63 patients with locally advanced rectal cancer scheduled for radical treatment." (PMID 23226389, 2012). "Additionally, the rectal cancer exhibited proficient DNA mismatch repair (pMMR) status, ERBB2 copy number amplification, and a missense mutation, while the KRAS, NRAS, and BRAF genes were wild-type." (PMID 39985003, 2025). "In addition, ERBB2 somatic mutations were also detected in his rectal cancer samples." (PMID 39985003, 2025). "In conclusion, we present a rare case of a de novo FAP patient with rectal cancer, characterized by double germline mutations in APC and BRCA2, alongside somatic ERBB2 mutations." (PMID 39985003, 2025). "In this study, we describe a case of an index patient with FAP and rectal cancer harboring germline mutations in both APC and BRCA2, as well as somatic ERBB2 mutations." (PMID 39985003, 2025). "In this case, sequencing revealed ERBB2 copy number amplification and a missense mutation (exon 17: c.G2033A; p.R648Q), and immunohistochemical analysis demonstrated HER2 positivity (3+) in the rectal cancer specimen." (PMID 39985003, 2025). "ERBB2 mutation was observed in one rectal cancer patient, but not in cases of other anatomic sites of origin." (PMID 26909603, 2016). "The five most frequently altered potentially targetable genes in colon and rectal cancer were PIK3CA (19.6% and 14.2%), PTEN (8.7% and 5.9%), ERBB2 (4.7% and 6.0%), EGFR (2.5% and 2.0%), and FGFR1 (2.0% and 2.7%)." (PMID 39865537, 2025). "A similar pattern was detectable in rectal cancer, where PIK3CA and PTEN alterations were significantly overrepresented in the RAS/BRAF‐altered subgroup and EGFR, ERBB2, FGFR1, and FGFR3 alterations were significantly overrepresented in the RAS/BRAF‐wt subgroup." (PMID 39865537, 2025).
salivary duct carcinoma (46 papers, 2009 to 2026). An aggressive, high grade adenocarcinoma that arises from the salivary glands. "Some of the most clinically meaningful changes associated with biomarker-directed therapy development have been reported in HER2-overexpressing/ERBB2-amplified salivary duct carcinoma with HER2-targeted therapies." (PMID 35267442, 2022). "The amplification of GRB7 and ERBB2 may also be an initial step in the malignant transformation of PA to CXPA (salivary duct carcinoma subtype)." (PMID 39384827, 2024).
uterine serous carcinoma (45 papers, 2010 to 2026). "In addition to these critical mutations, ErbB2 is amplified in 17–33% of carcinosarcomas, and uterine serous carcinomas." (PMID 32754300, 2020). "The authors reported a higher incidence of ERBB2/HER2 gene amplification in uterine serous carcinoma, clear cell carcinoma, and carcinosarcoma." (PMID 40731786, 2025). "The HER2 (ERBB2) gene is amplified in 17–33% of carcinosarcoma, uterine serous carcinoma, and a subset of high-grade endometrioid endometrial tumors." (PMID 35205261, 2022).
cardiomyopathy (43 papers, 2007 to 2025). A disease of the heart muscle or myocardium proper. "In mouse models, doxorubicin is known to cause cardiomyopathy and conditional cardiac knock out of Erbb2 results in dilated cardiomyopathy and increased sensitivity to doxorubicin-induced cell death." (PMID 29367538, 2017). "Our results, in conjunction with the demonstration that altered ErbB2 signaling underlies certain forms of mammalian cardiomyopathy, suggest that an evolutionarily conserved signaling mechanism may be necessary to maintain post-developmental cardiac function." (PMID 20523889, 2010). "Recent studies have shown that animal models with cardiac-restricted ErbB2 knockouts display a dilated-type cardiomyopathy phenotype 9." (PMID 40612676, 2025). "Degradation of endothelial ErbB2 results in autophagy of mitochondrial Trx2 that is required for protection against cardiomyopathy in I/R." (PMID 34039018, 2021). "A requirement for Erbb2 function in the atria may persist into the adult given the increased severity of cardiomyopathy arising from deletion of Erbb2 in cardiomyocytes of all chambers." (PMID 25269082, 2014). "The risks of cardiomyopathies developing, is further increased when Trastuzumab, a monoclonal antibody inactivating the transmembrane receptor tyrosine kinase HER2 or erbB2, is used in combination with daunorubicin and doxorubicin." (PMID 26580598, 2015). "ErbB2 inhibition has been shown to activate mitochondrial apoptosis by modulating the ratio of BCL-xL and -xS, resulting in cardiomyopathy, but the exact mechanism of trastuzumab induced cardiomyopathy is still unclear." (PMID 19284526, 2009).
serous carcinomas (40 papers, 2010 to 2025). "Overexpression of HER2/neu (ERBB2) is also linked to poorer survival, particularly in high-grade serous carcinomas, and may guide targeted therapy using trastuzumab." (PMID 40805172, 2025). "For instance, two-thirds of low-grade serous carcinomas carry mutations in KRAS, BRAF or ERBB2 (refs 17, 18, 19)." (PMID 23839242, 2013). "At the molecular genetic level, low-grade serous carcinomas are characterized by frequent somatic sequence mutations in genes that are involved in signal transduction including KRAS, BRAF, ERBB2, and PIK3CA." (PMID 22028712, 2012). "Molecularly, low-grade serous carcinomas generally have low levels of chromosomal instability and carry frequent mutations in KRAS, BRAF, and ERBB2, while high-grade serous carcinomas tend to have high levels of chromosomal instability and frequently show mutations in TP5310." (PMID 25314936, 2015). "The RAS-MAPK signaling pathway (genomic alterations of NF1 at 16% and KRAS at 12% with mutual exclusivity), the PI3K-mTOR pathway (PIK3CA at 12% and TSC2 at 8%), and certain receptor tyrosine kinases (ROS1 at 9% and ERBB2 at 8%) might be candidates for targeted therapy in serous carcinomas." (PMID 38201563, 2023).
liver cancer (39 papers, 2014 to 2025). An epithelial or non-epithelial malignant neoplasm that arises from the liver. "Several in vivo and in vitro studies have reported that ERBB2 is associated with liver cancer progression and epithelial–mesenchymal transitions." (PMID 37174100, 2023). "Subsequently, to investigate the effects of suppressing ERBB2 on the proliferation, migration, and invasion capabilities of liver cancer cells, we proceeded with additional cellular functional experiments." (PMID 38724606, 2024). "Western blot analysis revealed that CyclinE1, ERBB2, and EIF2α were expressed in the liver cancer cells." (PMID 39576845, 2024). "It has been found that mir-296-5p inhibits EMT related metastasis of liver cancer through ERBB2 signaling pathway." (PMID 32963562, 2020). "Interestingly, after treatment with ERBB inhibitors, the expected increase in proliferation, migration, and invasion abilities of liver cancer cells were suppressed, accompanied by a notable decrease in the expression levels of ERBB2 and its downstream signaling pathways." (PMID 38724606, 2024). "Through targeted inhibition of C-MYC and ERBB2 by MBP-1, the positive feedback of PI3K/AKT activation is reversed, thereby forming the mechanism of inhibiting the proliferation and migration of liver cancer cells as a whole." (PMID 39576845, 2024). "Both ERBB2 and NRG4 correlated with the Barcelona Clinic Liver Cancer stage, ERBB2 correlated with the tumor-maximal diameter, and NRG4 correlated with a tumor number." (PMID 37174100, 2023). "The current results confirm the findings of studies identifying AKT1, CDKN2A, ERBB2, and IL6 as critical markers for metastasis of pancreatic and liver cancers." (PMID 35154607, 2021). "For example, amplification of oncogenes (EFGR, ERBB2, and MYC) occurs via BFB in up to ~70% of diverse tumor types (including breast, colorectal, lung, and liver cancers)." (PMID 32687060, 2020). "A phase-II study of lapatinib, an inhibitor of EGFR and ERBB2, in patients with liver cancers revealed no response in CCA and a very low one in HCC (5%)." (PMID 27335842, 2014).
esophageal squamous cell carcinoma (38 papers, 2009 to 2025). Esophageal squamous cell carcinoma (ESCC) is a type of esophageal carcinoma (EC) that can affect any part of the esophagus, but is usually located in the upper or middle third. "Moreover, rs12976445 leads to a poor prognosis of esophageal squamous cell cancer, whereas a past report demonstrated that the level of mature miR-125a is reduced by rs12976445 G- > T, thus reducing the inhibitory effects of miR-125a on its downstream targets, such as ERBB2 and LIFR48–50." (PMID 35136075, 2022). "In esophageal squamous cell carcinoma, ERBB2 was identified as the target of FTO using m6A-seq and RNA-seq assays, and YTHDF1 then binds and stabilizes ERBB2 mRNA." (PMID 36360294, 2022).
gynecological cancers (37 papers, 2011 to 2026). "More importantly, overexpression of EGFR and ErbB2 has been associated with poor survival in gynecological cancer patients." (PMID 32754300, 2020). "Interestingly, it has been demonstrated that EGFR and ErbB2 overexpression, in association with the activation of PI3K and MAPK signaling pathways, increase resistance to cisplatin and paclitaxel in gynecological cancers." (PMID 28008141, 2017). "Another family of oncogenes to consider in gynecological cancers is the epidermal growth factor receptors EGFR (HER-1) and ErbB2 (HER-2), which are known for being cell-surface receptors tyrosine kinases being structurally similar." (PMID 28008141, 2017). "ERBB2, PIK3CA, ARID1A, and KRAS would be key molecular targets in gynecological cancers." (PMID 38201563, 2023).
bladder tumors (33 papers, 2006 to 2026). "As for ErbB2, its overexpression has been associated with BCa and risks of recurrence and progression but it is not yet clearly established as a molecular marker in recurrent bladder tumors as some studies showed varying results." (PMID 27660385, 2016). "Multiple studies of canine iUC tumors show that ERBB2 is over expressed in canine bladder tumors compared to normal bladder tissues." (PMID 38778091, 2024). "In all, this evidence suggests a “class-switch” from ErbB3 to EGFR/ErbB2 mediated ErbB signaling, mediated in part by collagen and fibronectin-stimulated integrin signaling, is a key mechanism promoting muscle-invasion of bladder tumors." (PMID 23383328, 2013). "As some bladder tumours overexpress ERBB2, it has been suggested that these may respond to ERBB2 inhibitors and therefore clinical studies have been initiated." (PMID 21364580, 2011). "Besides, ERBB2 also showed spatial patterns in liver and bladder tumor regions." (PMID 36243975, 2023).
urothelial bladder cancer (33 papers, 2009 to 2026). "The IHC results confirmed the protein expression and localization of the NECTIN4 and ERBB2 in the bladder urothelial carcinoma." (PMID 33490264, 2021). "To date, the efficacy of this therapy regimen in ERBB2 overexpressing urothelial bladder cancer is unclear." (PMID 34073233, 2021).
dilated cardiomyopathy (32 papers, 2006 to 2025). Cardiomyopathy which is characterized by dilation and contractile dysfunction of the left and right ventricles. "This was demonstrated by the development of dilated cardiomyopathy in postnatally mutated ErbB2 or ErbB4 mice." (PMID 38132657, 2023). "Preclinical studies demonstrated that ErbB2 knockout mice (ErbB2-CKO) showed poor survival and dilated cardiomyopathy whilst cardiomyocytes derived from ErbB2-CKO mice had increased susceptibility to the fatal cell damage induced by anthracyclines." (PMID 37444400, 2023). "Mice with a postnatal conditional ErbB2 mutation in ventricular cardiomyocytes show a severe dilated cardiomyopathy at the second month of age, indicating that ErbB2 has a cardioprotective role in adulthood." (PMID 32655416, 2020). "The importance of ErbB2 in the heart has been particularly emphasized by seminal studies that demonstrated that ErbB2 cardiac KO mice were affected by dilated cardiomyopathy, with increased susceptibility to anthracycline-induced damage to cardiomyocytes." (PMID 29467663, 2018). "Isolated cardiomyocytes from conditional mutants were more susceptible to anthracycline toxicity, demonstrating that ErbB2 signaling in cardiomyocytes is requisite for the prevention of dilated cardiomyopathy (DCM)." (PMID 28101782, 2017). "In mouse studies, knockout of the ErbB2 gene is lethal and knockout of ErbB2 in cardiac myocytes predisposes mice to dilated cardiomyopathy in response to cardiac stress (including exposure to anthracyclines)." (PMID 25885598, 2015). "Conditional Erbb2 mutation in ventricular cardiomyocytes leads to a severe dilated cardiomyopathy associated with the occurrence of sudden death, partially due to an impaired cardiac conduction system." (PMID 25269082, 2014). "ErbB2 is a target of chemotherapy in the treatment of several cancers and the inhibition of ErbB2 signaling by transgenic knock-out in mice and herceptin-treatment humans is associated with the development of dilated cardiomyopathy." (PMID 20523889, 2010). "Conditional inactivation of the erbB2 pathway in adult mice leads to dilated cardiomyopathy and has been linked to the cardiotoxicity of the therapeutic antibody trastuzumab (Herceptin®)." (PMID 21124978, 2010). "Over time, the ErbB2-deficient mice were found to develop features of dilated cardiomyopathy, including chamber dilation, wall thinning, and decreased contractility." (PMID 18231644, 2008). "Adult mice carrying a conditional ErbB-2 mutation develop severe dilated cardiomyopathy, usually in the second month of life." (PMID 16839426, 2006). "As shown by Özcelik and coworkers, loss of ErbB-2 in cardiomyocytes leads to physiological stress on the heart, which over time induces cardiac decompensation and dilated cardiomyopathy." (PMID 16839426, 2006). "However, ErbB2-deficient mice revealed several parameters of dilated cardiomyopathy, including chamber dilation, decreased contractility, and wall thinning, suggesting a possible role of the ErbB2 pathway in the prevention of DCM." (PMID 36292100, 2022). "ErbB2-deficient conditional mutant adult mice were viable and displayed no overt phenotype, but physiological analysis revealed a phenotype consistent with dilated cardiomyopathy." (PMID 28101782, 2017). "Another investigation revealed that patients with chronic HF due to dilated cardiomyopathy or ischemic etiology had significantly elevated serum levels of the soluble fraction of ErbB2 released from the membrane upon activation." (PMID 38132657, 2023). "Cardiomyocytes also express members of the ErbB2 family of proteins (HER1, HER2, and HER4), and ErbB2 knock out mice develop dilated cardiomyopathy." (PMID 37745115, 2023). "Despite low levels described in adulthood, ERBB2 appears to play a role in the prevention of dilated cardiomyopathy." (PMID 35497981, 2022).